SRPK1 (SRSF protein kinase 1)
Diseases named in the same sentence as SRPK1 in open-access papers (continued):
Sharing a sentence is not in itself a finding about the gene and the disease.
ovarian carcinoma (9 papers, 2012 to 2022). A malignant neoplasm originating from the surface ovarian epithelium. "SRPK1 silencing has been linked to platinum based chemotherapy sensitisation in breast, colorectal, pancreatic and ovarian cancer." (PMID 35583632, 2022). "Our findings also suggest that modulating SRPK1 levels to affect splicing factor activity and subsequent translation of mRNAs and expression of genes associated with growth control provides an opportunity to treat the abnormal growth of ovarian cancer cells." (PMID 23236423, 2012). "both explored the relationship between SRPK1 expression and the response of ovarian cancer cells to platinum-based chemotherapy." (PMID 35583632, 2022). "The earliest evidence showing that SRPK1 is a cisplatin sensitivity gene came from studies of S. cerevisiae and human ovarian carcinoma cells (A2780)." (PMID 36303126, 2022). "Wang F, etc found that lncRNA UCA1 affected platinum resistance in ovarian cancer by targeting the SRPK1/PI3K-Akt signaling pathway." (PMID 31391118, 2019). "Overexpression of UCA1 was shown to increase cisplatin resistance in ovarian cancer cells, possibly through the upregulation of SRPK1 expression, a splicing factor whose role in the cisplatin resistance of ovarian carcinoma cells remains controversial." (PMID 26992233, 2016). "We set out to further examine the relationship between the expression level of the SRPK1 gene and cDDP resistance in human ovarian cancer (OVCa)." (PMID 23236423, 2012). "In summary, our results demonstrate that a significant proportion of epithelial ovarian cancers overexpress SRPK1." (PMID 23236423, 2012). "Two of these studies found SRPK1 expression to be upregulated in ovarian cancer tissue." (PMID 35583632, 2022). "By Western blot analyses, SRPK1 protein was found to be overexpressed in 4 out of 6 ovarian cancer cell lines as compared with an immortalized ovarian surface epithelial cell line; and in 55% of ovarian tumor samples as compared with non-neoplastic ovarian tissue samples." (PMID 23236423, 2012). "In the present study we have tested whether serine-arginine protein kinase 1 (SRPK1), a major regulator of splicing factors, is involved in ovarian cancer progression and plays a role in chemo-sensitivity." (PMID 23236423, 2012). "Thus these results indicate that SRPK1 regulates the activities of proteins that mediate cell cycle progression through G1 to S phases, thereby regulating ovarian cancer cell growth." (PMID 23236423, 2012). "Together, these results suggest that elevated SRPK1 expression may play a role in ovarian tumorigenesis and SRPK1 may be a potential target for ovarian cancer therapy." (PMID 23236423, 2012). "Finally, in contrast to the yeast system, we made the surprising observation that inhibition of SRPK1 enhanced sensitivity to cDDP treatment, suggesting that SRPK1 may be a target for therapy of ovarian cancer." (PMID 23236423, 2012). "Using a Cox regression model we did not observe a clear correlation between SRPK1 level and overall (p = 0.26) or disease free (p = 0.62) survival in the ovarian cancer patients." (PMID 23236423, 2012).
hepatocellular carcinoma (8 papers, 2015 to 2024). A malignant tumor that arises from hepatocytes. "Furthermore, SRPK1 had been reported to associate with hepatocellular carcinoma progression and poor patient survival." (PMID 32194790, 2020). "miRNA-1296 inhibits metastasis and the epithelial-mesenchymal transition of hepatocellular carcinoma cells by targeting the SRPK1-mediated PI3K/AKT pathway." (PMID 30530570, 2019). "In clinical samples of hepatocellular carcinoma, SRPK1 has been found upregulated at both mRNA and protein levels." (PMID 26273588, 2015). "Five studies evaluated the role of SRPK1 in hepatocellular carcinoma (HCC)." (PMID 35583632, 2022). "Importantly, in human hepatoma cells the bulk of HBc appeared as highly phosphorylated as SRPK1-coexpressed HBc." (PMID 30566530, 2018). "The bulk of capsids from human hepatoma cells was similarly highly, yet non-identically, phosphorylated as by SRPK1." (PMID 30566530, 2018). "Importantly, the new tools indicated that the bulk of HBc in human hepatoma cells is similarly highly phosphorylated as the recombinant SRPK1 phosphorylated protein, albeit in a non-identical pattern." (PMID 30566530, 2018).
leukemia (7 papers, 2015 to 2025). A malignant (clonal) hematologic disorder, involving hematopoietic stem cells and characterized by the presence of primitive or atypical myeloid or lymphoid cells in the bone marrow and the blood. "Furthermore, SRPK1 has been implicated in other leukaemias, including chronic myeloid leukaemia (CML)." (PMID 36895328, 2023). "Serine/arginine-rich protein kinase 1 (SRPK1), a key splicing regulator, is reported to be overexpressed in leukemia and other cancer types, which suggests the therapeutic potential of targeting SRPK1." (PMID 36303126, 2022). "Considering leukemias, SRPK1 has been found to be overexpressed in patients with acute lymphoblastic leukemia and chronic myeloid leukemia." (PMID 26244849, 2015). "In summary, we suggest that in the context of AML, and potentially in other types of leukaemia, there may be therapeutic potential in targeting SRPK1 and other splice factor kinases." (PMID 36895328, 2023). "Indeed, SRPK1 inhibition synergised with inhibitors of BRD proteins in reducing the growth of leukaemia cells." (PMID 34092037, 2021). "SRPK1‐upregulation was documented in several human solid tumours and in leukaemia." (PMID 34092037, 2021). "Two other ATP competitive inhibitors of SRPK1, SPHINX and its derivative SPHINX‐31, elicited anti‐tumoral effects in models of leukaemia and solid tumours." (PMID 34092037, 2021). "Based on these accumulated SRPK1 and SRPK2 gene expression data, we aimed to investigate the cytotoxic effect of the SRPK inhibitor SRPIN340 on leukemia cells." (PMID 26244849, 2015). "Taken together, these results demonstrate that the expression of SRPK1 and SRPK2 are proportionally distinct among the leukemia cells analyzed." (PMID 26244849, 2015). "Previous investigations have described the overexpression of SRPK1 and SRPK2 in leukemia and other cancer types, suggesting that they would be useful targets for developing novel antitumor strategies." (PMID 26244849, 2015). "In the present study we have focused on evaluating the effect of the SRPK1 inhibitor SPHINX on two well-studied and established cell line models of leukaemia; Kasumi-1, representing acute myeloid leukaemia (AML), and K562 representing chronic myeloid leukaemia (CML)." (PMID 36895328, 2023). "Considering this structural similarity, the position of the ATP analog, previously co-crystallized with SRPK1, allowed the prediction of its binding site into SRPK2, the paralog chosen to be studied herein, because its mechanisms in leukemia tumorigenesis have been previously well determined." (PMID 26244849, 2015). "To expand previous findings and gain further information about the relative proportion between SRPK1 and SRPK2 expression among the leukemia cells used in this work, we evaluated the expression of SRPK1 and SRPK2 in a panel of leukemia cell lineages from different origins and genetic backgrounds." (PMID 26244849, 2015).
gastric cancer (6 papers, 2017 to 2023). A primary or metastatic malignant neoplasm involving the stomach. "DNA microarray analysis identified a potential link between SRPK1 expression and the proliferation of a number of small nucleolar RNA (SnoRna), including SnoRnaD10, SnoRnaA42 and SnoRnaA74A all of which have been linked to gastric cancer progression." (PMID 35583632, 2022). "SRPK1 is frequently overexpressed in gastric cancer, resulting in tumor cell growth by regulating the small nucleolar RNA expression." (PMID 37377953, 2023). "IHC analysis found an antagonistic relationship to exist between SRPK1 and miRNA-126 expression, whereby miRNA-126 is underexpressed and SRPK1 overexpressed in gastric cancer tissue." (PMID 35583632, 2022). "A similar function of SRPK1 has been reported in gastric cancer, SRPK1 knocking down increased G1/G0 phase arrest in gastric cancer cells." (PMID 36038837, 2022). "SRPK1 knockdown was found to suppress gastric cancer cell proliferation and tumour growth, both in vitro and in vivo." (PMID 35583632, 2022). "All included studies found SRPK1 to be overexpressed in gastric cancer tissue compared to matched normal tissue." (PMID 35583632, 2022). "Immunostaining analysis showed that the expression level of SRPK1 protein in histological sections was significantly correlated with clinical characteristics and reduced survival time of gastric cancer patients." (PMID 28977917, 2017). "Four studies were identified which examined the role of SRPK1 in gastric cancer development." (PMID 35583632, 2022). "SRPK1 has been previously characterized to drive cell proliferation, migration, and invasion in colorectal and gastric cancers suggesting that the fusion protein may have oncogenic consequences in the SNUC cell line." (PMID 34051734, 2021). "The existence and role of SRPK1 in gastric cancer (GC) hasn’t been reported." (PMID 28977917, 2017). "Protein phosphatase 2 (PP2A) and dual-specificity phosphatase (DUSP) expression were found to alleviate the oncogenic effects of SRPK1 expression in gastric cancer cells, though their exact inhibitory roles were not fully determined in this study." (PMID 35583632, 2022).
COVID-19 (4 papers, 2021 to 2024). A disease caused by infection with severe acute respiratory syndrome coronavirus 2. "Similarly, network pharmacology methods have accentuated a close nexus between COVID-19 and serine/arginine-rich splicing factor protein kinase-1 (SRPK1), a gene intimately involved in SARS-CoV-2 replication through phosphorylation of the N protein." (PMID 38414855, 2024). "SRPK1 is highly expressed in most tissues and mostly associated with DNA and RNA processing, while SRPK3 is involved more specifically in muscle related functions and as such could be linked to cardiac complications observed in some COVID-19 patients." (PMID 34019655, 2021). "SRPK1, CSGALNACT2, B4GALT5, MEGF9, and KLF5 have increased mRNA expression in patients with severe COVID-19 compared with mild and non-COVID-19 patients." (PMID 38262689, 2024).
triple-negative breast carcinoma (4 papers, 2020 to 2023). An invasive breast carcinoma which is negative for expression of estrogen receptor (ER), progesterone receptor (PR), and human epidermal growth factor receptor 2 (HER2). "The inhibition of SRPK1 blocked the metastatic properties of TNBC cells, which led to the thought that LIMK2 promotes the metastatic progression of triple-negative breast cancer by activating SRPK1." (PMID 36899941, 2023). "Pharmacological inhibition of SRPK1 in triple negative breast cancer cell lines results in a reduced capacity for invasion and migration, supporting a link between SRPK1 and LIMK2 signalling in the context of metastatic spread in triple negative breast cancer." (PMID 35583632, 2022). "Serine-arginine protein kinase 1 (SRPK1) has also been described as a target of LIMK2, and this connection plays a major role in triple negative breast cancer metastasis." (PMID 36899941, 2023).
chronic myeloid leukaemia (3 papers, 2022 to 2023). "SRPK1 silencing is associated with a significant increase in apoptosis in K562 chronic myeloid leukaemia cells." (PMID 35583632, 2022).
Denys-Drash syndrome (3 papers, 2015 to 2021). Denys-Drash syndrome (DDS) is a rare urogenital disorder characterized by the association of diffuse mesangial sclerosis (DMS), male pseudohermaphroditism with a 46,XY karyotype, and nephroblastoma. "In contrast, SRPK1 modulates alternative splicing of VEGF pre-mRNA, which leads to excessive angiogenesis in patients with Denys-Drash Syndrome harboring a mutation of the tumor suppressor gene WT1." (PMID 25581376, 2015). "WT1 is an inhibitor of SRPK1 phosphorylation; Denys Drash Syndrome patients have a mutation in WT1, resulting in no inhibition of SRPK1 and an increased VEGF-A165/VEGF-A165b ratio." (PMID 30865689, 2019).
glioblastoma (3 papers, 2017 to 2024). The most malignant astrocytic tumor (WHO grade IV). "Whether the virus induces glioblastoma and whether SRPK1 is synergistically associated with virus-induced tumors are still subjects that require further investigation." (PMID 38397980, 2024). "However, the precise and effective molecular mechanisms underlying SRPK1 regulation of glioblastoma cell proliferation, invasion, and migration remain unclear, and the signaling pathways associated with SRPK1 have not been thoroughly explored." (PMID 38397980, 2024). "In subsequent experiments, we confirmed that SRPK1 can participate in the malignant progression of glioblastoma by regulating the Wnt/β-catenin and JAK-2/STAT-3 pathways." (PMID 38397980, 2024). "Our experiments were systematic and revealed the role of SRPK1 in glioblastoma, elucidating its specific regulatory pathways and validating them using animal models." (PMID 38397980, 2024). "Analysis of the Cancer Genome Atlas (TCGA) database revealed that SRPK1 expression is highest in glioblastoma among 19 types of cancer." (PMID 38397980, 2024). "We believe that understanding the signaling pathways through which SRPK1 regulates the occurrence and development of glioblastoma is of great importance and provides a theoretical basis for the development of targeted therapies against SRPK1." (PMID 38397980, 2024). "Compared with normal tissues (n = 37), TCGA glioblastoma (n = 192) showed a significant increase in SRPK1 mRNA." (PMID 38397980, 2024). "A 2020 study identified SRPK1 as a potential therapeutic target in glioblastoma, with the SRPK1 inhibitor SPHINX31 showing promising results in preclinical models." (PMID 37568654, 2023). "Moreover, SRPK1 play a critical role in EMT process of human glioblastoma." (PMID 28606154, 2017).
malaria (3 papers, 2014 to 2022). Malaria is a serious and sometimes fatal disease caused by a parasite that commonly infects a certain type of mosquito which feeds on humans. "In this study, we functionally characterize SRPK1 of the human malaria parasite Plasmodium falciparum." (PMID 36094218, 2022). "In the rodent malaria parasite P. berghei, SRPK1 has a minor function during asexual blood-stage development, and the peak replication rate during exponential parasite growth is not reduced." (PMID 36094218, 2022).
renal cell carcinoma (3 papers, 2021 to 2024). "One study examined the role of SRPK1 in renal cell carcinoma(RCC)." (PMID 35583632, 2022).
retinoblastoma (3 papers, 2012 to 2022). A malignant tumor that originates in the nuclear layer of the retina. "A single publication examined the role of SRPK1 in retinoblastoma." (PMID 35583632, 2022). "Similarly, decreased SRPK1 may also lead to the cisplatin-resistance of retinoblastoma, indicating the complicated crosstalk between SRPK1 and chemotherapy resistance." (PMID 35192432, 2022).
testicular germ cell tumor (3 papers, 2019 to 2022). A germ cell tumor arising from the testis. "A single study evaluated SRPK1 expression in testicular germ cell tumors (GCTs)." (PMID 35583632, 2022). "In contrast, the function of SRPK1 seems different in testicular germ cell tumors." (PMID 35192432, 2022). "In patients with NSGCTs (non-seminomatous germ cell tumors) of the testis, low SRPK1 expression was associated with resistance to chemotherapy, whereas high SRPK1 expression characterized the tumors that responded to therapy." (PMID 31861708, 2019).
Wilms tumor (3 papers, 2013 to 2022). An embryonal neoplasm characterized by the presence of epithelial, mesenchymal, and blastema components. "In these nephroblastomas tumors SRPK1 transcriptional upregulation is driven by the mutated transcription factor WT1, and its splicing activity is fundamental for the high levels of vascularization required by these tumors." (PMID 24069033, 2013). "A similar regulation has been described in Wilms Tumor, wherein SRPK1 promotes the production of the proangiogenic isoform VEGF165 of the VEGFA gene through the phosphorylation and nuclear translocation of SRSF1." (PMID 24069033, 2013).
age-related macular degeneration (2 papers, 2022 to 2023). Age-related loss of vision in the central portion of the retina (macula), secondary to retinal degeneration. "Gray and coworkers demonstrated that JH-VII-139-1 potently inhibits SRPK1 with an IC50 value of 1.1 nM and blocks angiogenesis in an age-related macular degeneration (AMD) animal model." (PMID 36839704, 2023).
breast tumors (2 papers, 2012 to 2020). "Moreover, a few genes involved in modulation of the extracellular matrix (ADAMTS4, MMP1, MMP3, and angiogenesis (MFAP5, SFRP2, SRPK1, VEGF, and CHI3L1) were found to be expressed at higher levels in the primary breast tumors compared with the bone metastases." (PMID 23174366, 2012).
cervical cancer (2 papers, 2022 to 2025). A primary or metastatic malignant neoplasm involving the cervix. "SRPK1 inhibition may remodel the cervical cancer transcriptome in an HPV-linked manner, with SiHa cells exhibiting changes consistent with suppression of oncogenic signaling, whereas C33A cells adapt through translational and metabolic reprogramming." (PMID 41551143, 2025). "Here in the current study, we initially investigate the expression and tumor-related function of SRPK1 in cervical cancer." (PMID 35192432, 2022). "HPV16+ SiHa and HPV- C33A cervical cancer cells were treated with the SRPK1 inhibitor, SPHINX31." (PMID 41551143, 2025). "Considering its reported role in other malignancies, we hypothesized that SRPK1 may participate in cervical cancer progression." (PMID 35192432, 2022). "Therefore, we sought to determine how SRPK1 inhibition differentially remodels gene expression and alternative splicing in HPV+ versus HPV- cervical cancer cells." (PMID 41551143, 2025). "We hypothesized that SRPK1 may be aberrantly expressed in CESC and may participate in cervical cancer progression." (PMID 35192432, 2022). "Till now, there is no study reporting the expression and function of SRPK1 in cervical cancers." (PMID 35192432, 2022).
esophageal SCC (2 papers, 2022). "Elevated SRPK1 protein expression is associated with esophageal squamous cell carcinoma (SCC)." (PMID 35583632, 2022). "SRPK1 silencing inhibits proliferation, invasiveness and migration and induces apoptosis across esophageal SCC cell lines." (PMID 35583632, 2022).
frontotemporal dementia (2 papers, 2020 to 2024). Frontotemporal dementia (FTD) comprises a group of neurodegenerative disorders, characterized by progressive changes in behavior, executive dysfunction and language impairment, as a result of degeneration of the medial prefrontal and frontoinsular cortices. "A previous study showed that SRPK1 controls the alternative splicing of exon 10, which plays a significant role in frontotemporal dementia and AD." (PMID 38376036, 2024). "Previous research has demonstrated that SRPK1 controls the alternative splicing of exon 10, which is related to the etiology of tauopathies such as frontotemporal dementia and Alzheimer's disease (AD)." (PMID 38376036, 2024).
lung adenocarcinoma (2 papers, 2015 to 2024). A carcinoma that arises from the lung and is characterized by the presence of malignant glandular epithelial cells. "However, the m6A modification of SRPK1 and its association with the mechanism of in lung adenocarcinoma (LUAD) remains unclear." (PMID 39095708, 2024).